DEPP1 (DEPP autophagy regulator 1)
Description:
Acts as a critical modulator of FOXO3-induced autophagy via increased cellular ROS.
Synonyms: FIG; C10orf10; DEPP; Fseg
Tractability: No criterion of Open Targets' tractability assessment is met for any kind of drug.
Gene: Protein-coding gene on chromosome 10 (44,970,981 to 44,978,809, reverse strand). Ensembl gene ENSG00000165507.
Subcellular location: Cytoplasm; Peroxisome; Mitochondrion
Subcellular location (Human Protein Atlas): Mitochondria; Vesicles
Gene Ontology:
Biological process: regulation of autophagy
Cellular component: cytoplasm; mitochondrion; peroxisome
Genetic constraint (gnomAD): Loss-of-function variants: 0 observed, 0.8 expected, observed/expected ratio (o/e) 0, 90% interval 0 to 1.77. That is too few expected variants to judge how well the gene tolerates losing a copy. Missense variants: 267 observed, 289.12 expected, observed/expected ratio (o/e) 0.92, 90% interval 0.83 to 1.02. Synonymous variants: 117 observed, 116.4 expected, observed/expected ratio (o/e) 1.01, 90% interval 0.86 to 1.17.
Homologues: Orthologues: chimpanzee DEPP1 (97% identical), macaque DEPP1 (94% identical), dog DEPP1 (66% identical), pig DEPP1 (64% identical), rat Depp1 (59% identical), mouse Depp1 (58% identical), rabbit DEPP1 (58% identical), guinea pig DEPP1 (54% identical), zebrafish si:dkeyp-72g9.4 (20% identical), zebrafish si:ch73-6k14.2 (17% identical).
Diseases named in the same sentence as DEPP1 in open-access papers:
DEPP1 is named in the same sentence as 38 diseases in open-access papers, as found by Europe PMC text mining. Sharing a sentence is not in itself a finding about the gene and the disease. The quoted sentences say what the papers report.
neuroblastoma (7 papers, 2014 to 2025). Neuroblastoma (NB) is the most common solid, extracranial childhood tumor. "DEPP1 sensitizes neuroblastoma cells for ROS and is strongly induced by FOXO3 via three functional FOXO consensus sequences in its promoter." (PMID 31789593, 2019).
glioma (3 papers, 2022 to 2025). A benign or malignant brain and spinal cord tumor that arises from glial cells (astrocytes, oligodendrocytes, ependymal cells). "Increased C10orf10 levels (DEPP Autophagy Regulator 1, DEPP1) correlated with the shorter survival time of patients with primary gliomas." (PMID 39189258, 2024). "Through TCGA database, we identified that the eight key genes (PCDH18, PPL, DEPP1, VASN, KCNE4, MYBPH, C5AR2, and MARCH4) were associated with the survival of patients with glioma." (PMID 39281062, 2022). "Overexpression of PCDH18, PPL, DEPP1, VASN, KCNE4, MYBPH, and C5AR2 genes or low expression of MARCH4 gene in glioma patients was associated with poor survival." (PMID 39281062, 2022). "Overexpression of PCDH18, PPL, DEPP1, VASN, KCNE4, MYBPH, and C5AR2 in glioma and low expression of MARCH4 were associated with poor survival." (PMID 39281062, 2022). "A previous study showed that the knockdown of DEPP1 could significantly inhibit the growth of glioma cells both under hypoxia and normoxia." (PMID 40052358, 2025). "The IHC findings confirmed the increased expression of AEBP1, DCTD, DEPP1, DUSP6, FKBP9, and UGCG with the up‐regulation of glioma grades." (PMID 40052358, 2025). "Of the 508 patients with glioma, the expression of PCDH18 (p < 0.001), DEPP1 (p < 0.001), VASN (p < 0.001), KCNE4 (p < 0.01), MYBPH (p < 0.001) and MARCH4 (p < 0.01) genes was significantly different between G2 and G3." (PMID 39281062, 2022).
endometriosis (2 papers, 2015 to 2020). The growth of functional endometrial tissue in anatomic sites outside the uterine body. "SPP1, LIF, TCN1 and CLDN4 were common to adenomyosis and healthy groups of genes, while ANXA2, EDNR8, MMP26, DEPP1, ABCC3, CDA and SLC1A1 were common to endometriosis and healthy groups." (PMID 32933042, 2020).
gastric cancer (2 papers, 2023 to 2024). A primary or metastatic malignant neoplasm involving the stomach. "Higher levels of PAPPA2, MPO, MAGEA11, DEPP1, CPZ, and COLEC12 and lower level of CYTL1 were proven in gastric cancer cells versus controls." (PMID 37124627, 2023). "In contrast to gastric mucosa epithelial cell line GES-1, transcriptional levels of PAPPA2, MPO, MAGEA11, DEPP1, CPZ, and COLEC12 were higher in gastric cancer cell lines HGC-27, MKN-28 and AGS, with lower transcriptional level of CYTL1." (PMID 37124627, 2023). "This study experimentally verified the levels of DNA repair-relevant genes, with higher levels of PAPPA2, MPO, MAGEA11, DEPP1, CPZ, and COLEC12 and lower level of CYTL1 in gastric cancer cells versus controls." (PMID 37124627, 2023).
ischemic cardiomyopathy (2 papers, 2024 to 2025). Ischemic cardiomyopathy is a cardiomyopathy in which a weakness in the muscle of the heart due to inadequate oxygen delivery to the myocardium with coronary artery disease being the most common cause. "Current studies on Depp1 have focused mainly on oxidative stress and autophagy in cancer and ischemic cardiomyopathy." (PMID 39852377, 2025). "Moreover, DEPP1 abundance is increased in ischemic cardiomyopathy patient biopsies, and this correlates with dysregulated mitochondrial and peroxisomal protein abundance." (PMID 38881449, 2024). "Because HIF activation is a predictable consequence of impaired oxygen delivery, we asked whether DEPP1 levels are increased in human ischemic cardiomyopathy." (PMID 38881449, 2024).
cardiomyopathy (1 paper, 2024). A disease of the heart muscle or myocardium proper. "It will therefore be of interest to determine whether DEPP1 loss is cardioprotective in other models of acute or chronic ischemia as well in the setting of other cardiomyopathies." (PMID 38881449, 2024).
cervical cancer (1 paper, 2023). A primary or metastatic malignant neoplasm involving the cervix. "The results showed that high expression of MYH1, MYH4, FGG, and DEPP1 was associated with shorter overall survival of patients with cervical cancer; high expression of SULT1E1, RAB3C, CXCR3, and PROX2 was associated with longer overall survival of patients with cervical cancer." (PMID 37350944, 2023). "High expression of MYH1, MYH4, FGG, DEPP1, and ZBTB16 was associated with shorter overall survival of patients with cervical cancer; high expression of SULT1E1, RAB3C, CXCR3, and PROX2 was associated with longer overall survival of patients with cervical cancer." (PMID 37350944, 2023).
depression (1 paper, 2025). "Depp1 may be associated with synaptic damage in depression along with hyperglycemia, but its specific neuronal populations and function need to be further examined." (PMID 39852377, 2025). "In conclusion, our research reveals that an upregulation of Depp1 in the mPFC is closely involved in the co-occurrence of depression and diabetes." (PMID 39852377, 2025). "Therefore, in this study, we investigated the impact of Depp1 on the synthesis of synaptic proteins in both depression and diabetes models." (PMID 39852377, 2025). "Further identification of the biomarkers that significantly correlated with the expression level of DEPP1 in the mPFC will benefit the diagnosis of possible comorbidity in depression and diabetes and will facilitate the research and development of an agent to achieve targeting effects." (PMID 39852377, 2025).
fibrosis (1 paper, 2024). the formation of excess fibrous connective tissue in an organ or tissue in a reparative or reactive process. "Similarly, whole-body Depp1 loss reduced cardiac fibrosis and apoptosis in hearts lacking pVHL." (PMID 38881449, 2024).
Hyperglycemia (1 paper, 2025). An increased concentration of glucose in the blood. "Depp1, a DEPP autophagy regulator, is highly expressed in the mPFC of depressed mice and diabetic mice and potentially contributes to both despair behavior and hyperglycemia." (PMID 39852377, 2025).
osteosarcoma (1 paper, 2024). A usually aggressive malignant bone-forming mesenchymal neoplasm, predominantly affecting adolescents and young adults. "Our work was restricted to isolated cardiomyocytes, immortalized U2OS osteosarcoma cells, and whole-body Depp1 knockout mice." (PMID 38881449, 2024).
tumor (5 papers, 2014 to 2023). "Univariate independent prognostic analysis showed that age (p < 0.001), tumor grade (p < 0.001), PCDH18 (p < 0.05), PPL (p < 0.01), DEPP1 (p < 0.01), VASN (p < 0.001), KCNE4 (p < 0.001), MYBPH (p < 0.001), C5AR2 (p < 0.01), and MARCH4 (p < 0.01) gene expression levels were significantly different." (PMID 39281062, 2022).
metabolic disorders (2 papers, 2022 to 2023). "It has been demonstrated that the DEPP1 protein plays a crucial role in coordinating thermogenesis by regulating adipocyte programs and may offer a potential target for treating metabolic disorders." (PMID 37868195, 2023).
infection (1 paper, 2024). The state of being infected such as from the introduction of a foreign agent such as serum, vaccine, antigenic substance or organism. "These proteins were then introduced into DEPP1 knockout cardiomyocytes by lentiviral infection followed by fluorescence cell sorting for cells in which the levels of the exogenous proteins approximated endogenous DEPP1 levels." (PMID 38881449, 2024).
DEPP1 also shares sentences with these, for which no sentence is quoted: cancer (7 papers); colon cancer (6); breast carcinoma (4); Insulin resistance (2); Obesity (2); adenomyosis (1); Arthritis (1); atherosclerosis (1); Atrophy (1); brain trauma (1); breast neoplasm (1); Cerebral ischemia (1); Cholecystitis (1); diabetes (1); glioblastoma (1); heart failure (1); hepatocellular carcinoma (1); ischemia (1); leukemia (1); melanoma (1); neuronal tumor (1); osteoarthritis (1); prostate carcinoma (1); retinal diseases (1).